GLO1 (glyoxalase I)
Diseases named in the same sentence as GLO1 in open-access papers (continued):
Sharing a sentence is not in itself a finding about the gene and the disease.
Pca (1 paper, 2013). "All results, except those on the association of GLO1 polymorphism with PCa risk, withstood correction for multiple testing (p<0.05)." (PMID 24040147, 2013). "The results of our exploratory study point out a significant role for GLO1 in PCa progression, providing an additional candidate for risk assessment in PCa patients and an independent prognostic factor for survival." (PMID 24040147, 2013). "As to survival analysis, we found that GLO1 −419 A allele was significantly associated with an unfavourable survival prognosis in patients with localized (T1/T2) or low grade (GS 2–6) PCa." (PMID 24040147, 2013). "In the present study we evaluated, for the first time to our knowledge, the association between GLO1 −419C>A polymorphism and oxidative stress levels in PCa progression." (PMID 24040147, 2013). "A study on the association of GLO1 polymorphism and PCa risk and survival in selected subgroups was also performed." (PMID 24040147, 2013). "Since this is the first study examining the association between GLO1 −419C>A polymorphism and PCa, additional research is required." (PMID 24040147, 2013). "We would like to emphasize that the present work, providing biological plausibility to the association of GLO1 polymorphism with the progression or to the combination of all the analyzed polymorphisms with the risk of PCa, bring up a valid contribution to the study of genetic associations." (PMID 24040147, 2013). "Secondly, since we believe that the combination of more polymorphisms in each single case, with respect to a single one, may be a more predictive factor for the association to the risk of PCa, we evaluated such a combination, also including GLO1 polymorphism." (PMID 24040147, 2013). "Less important was the association of GLO1 polymorphism with the risk of PCa development." (PMID 24040147, 2013). "In conclusion, our study pointed out a significant role for GLO1 in PCa progression and that GLO1 −419A risk allele may be an independent prognostic factor for survival." (PMID 24040147, 2013). "Since our initial results pointed out a role for GLO1 in PCa progression, providing a biological background to the possible association of GLO1 A111E polymorphism with PCa, we, additionally, examined its association with progression, evaluated by stage and grade." (PMID 24040147, 2013). "Therefore, it was reasonable to expect that the presence of a lower activity form of GLO1– the GLO1 A allele – might be predictive about severe consequences for an individual’s PCa risk of progression." (PMID 24040147, 2013). "Since these in vitro results appeared to support the potential association of GLO1 polymorphism with progression, we performed measurements of the same parameters in blood samples and cells from urine sediments of patients with localized and locally advanced or low, intermediate and high grade PCa." (PMID 24040147, 2013). "In the present study, we hypothesized that GLO1 polymorphism, linked to a decrease of GLO1 enzymatic activity, and, consequently, to an accumulation of GLO1-related pro-oxidative AP, could be associated with oxidative stress induction, thus counting as a novel mechanism in PCa progression." (PMID 24040147, 2013). "GLO1 A111E polymorphism has been studied in some human disorders, including cancer, however, to the best of our knowledge, its role in PCa has never been investigated before." (PMID 24040147, 2013). "Therefore, our results suggested a significant role for GLO1 in the progression rather than in the development of PCa." (PMID 24040147, 2013).
renal carcinoma (1 paper, 2010). A carcinoma arising from the epithelium of the renal parenchyma or the renal pelvis. "Higher levels of GLO-1 have been found in a broad array of tumors when compared to their normal tissue counterparts including prostate, colon, and renal cancers." (PMID 20454582, 2010).
retinitis pigmentosa (1 paper, 2020). Retinitis pigmentosa (RP) is an inherited retinal dystrophy leading to progressive loss of the photoreceptors and retinal pigment epithelium and resulting in blindness usually after several decades. "The exposure to A2E highlighted significant expression differences and splicing events in 370 GLO1 first-neighbor genes, and 23 of them emerged from pathway clustered analysis as main candidates to be associated with retinitis pigmentosa." (PMID 32413970, 2020). "GLO1 mutations have been linked to several human diseases, but very little is known about the influence of this enzyme in eye-related disorders, especially about genetic ones such as retinitis pigmentosa (RP)." (PMID 32413970, 2020). "To clarify the role of GLO1 in retinitis pigmentosa onset and progression, we treated human retinal pigment epithelium cells by the oxidant agent A2E." (PMID 32413970, 2020). "Even if it is known that GLO1 defects could play a role in retinitis pigmentosa, contributing to the accumulation of AGEs in the retina, very little is known about molecular mechanisms and pathways by which GLO1 determines its deleterious effects." (PMID 32413970, 2020).
short bowel syndrome (1 paper, 2025). "In certain cases of short bowel syndrome, D-lactate can reach a 3 mM concentration or higher in plasma; however, the main route for D-lactate formation is through glyoxalase metabolism of SDL, the product of Glo1 and the substrate of Glo2." (PMID 40867843, 2025).
skin cancer (1 paper, 2020). "Due to the high expression of Glo1 in skin malignancies, Glo1 has become a novel target for the development of drugs against skin cancer." (PMID 33396745, 2020). "Glo1 is overexpressed in SCC, BCC, and verrucous carcinoma tissues, whereas its expression is lower in benign skin neoplasms and normal skin." (PMID 33396745, 2020). "In contrast to Glo1, the role of Glo2 in skin cancer has not yet been researched." (PMID 33396745, 2020).
stomach diseases (1 paper, 2016). "Interestingly, though proteins such as Glyoxalase I (GLO1, DD = 3), Nitric Oxide Synthase (NOS1, DD = 3), Matrix metalloproteinase-9 (MMP9, DD = 2) and Acetylcholinesterase (ACHE, DD = 2) do not have high topological properties, they are all the therapeutic targets of stomach diseases." (PMID 27597117, 2016).
xerostomia (1 paper, 2025). Dryness of the mouth resulting from reduced salivary secretion. "The downregulation of key proteins involved in oxidative stress and neurodegenerative diseases, encoded by PARK7, GLO1, GLUD2, VDAC2, UQCRC1, and UNC5C, including the 20S proteasome core complex proteins, highlights a possible mechanistic link to xerostomia pathophysiology." (PMID 40806170, 2025). "Likewise, Glyoxalase I is essential to MGO detoxification and prevention of AGE formation, where its reduced expression suggests an important dysregulation of glyoxalase pathways in xerostomia patients." (PMID 40806170, 2025).
cancer (92 papers, 2008 to 2026). A tumor composed of atypical neoplastic, often pleomorphic cells that invade other tissues. "This research aims to add to the current state of knowledge regarding the association between GLO-1 and cancer, as well as its potential clinical implications." (PMID 40727469, 2025). "GLO-1 has been implicated in protecting cancer cells from the cytotoxic effects of anticancer drugs in various malignancies." (PMID 40727469, 2025). "By contrast, the overexpression of GLO1 is associated with growth, the progression of several types of cancer, and resistance to therapy, as bypassing glycolysis allows tumor cells to promote increased demands for NADPH in maintaining the redox state." (PMID 40002398, 2025). "Although our analyses demonstrate notable associations between GLO-1 expression and several cancer-related features, it is important to recognize that these findings remain correlative and do not establish causality." (PMID 40727469, 2025). "This context-dependent role of GLO-1 in cancer necessitates further investigation into the underlying mechanisms and its therapeutic potential in this context." (PMID 40727469, 2025). "This increased GLO-1 expression is associated with both cancer development and resistance to chemotherapy." (PMID 40727469, 2025). "GLO-1 dysregulation has been implicated in various cancers, prompting the explorationof pharmacological and genetic strategies targeting cancer cells via GLO-1 modulation." (PMID 40727469, 2025). "The dysregulation of Glo1 expression has been observed in various cancer types, with both increased and decreased expression associated with specific cancer phenotypes." (PMID 38785990, 2024). "Glo1 overexpression has been associated with several cancers and multidrug resistance, presenting itself as a potential therapeutic target." (PMID 38398772, 2024). "Glo-1 over-expression in cancer has been considered as an independent risk factor associated with poor prognostic and multi-drug resistance." (PMID 39682111, 2024). "Conversely, decreased GLO1 expression has been associated with more aggressive cancer phenotypes, suggesting a complex role for the glyoxalase system in cancer progression." (PMID 38785990, 2024). "Herein, overexpression of GLO1 is permissive for carcinoma cells with high glycolytic activity and is a cause of multi-drug resistance." (PMID 36612084, 2022). "To explore the clinical relevance of baseline Glo1 expression in clinical cancer chemotherapy, we investigated association of Glo1 expression with cancer patient survival receiving chemotherapy in the KM Plotter database." (PMID 34790575, 2021). "This is the first time clinical expression of Glo1 in tumors has been linked to survival in clinical cancer chemotherapy." (PMID 34790575, 2021). "We have shown that cancer cells express AKRs that represent a compensatory mechanism in case of GLO1 loss or decreased activity." (PMID 28916747, 2017). "Recent studies have reported that over-expression of GLO1 is associated with cancer progression and drug resistance." (PMID 22479608, 2012). "Furthermore, we analyzed the complex interplay between cancer immunotherapy and GLO-1 expression by examining its association with key immunotherapeutic biomarkers, including TMB, MSI, and a panel of ICPs." (PMID 40727469, 2025). "Furthermore, evidence suggests that the GLO1 gene is a key hotspot for copy-number variations linked to multidrug resistance in cancer chemotherapy." (PMID 40002398, 2025). "Furthermore, elevated Glo1 expression is associated with multidrug resistance in cancer chemotherapy." (PMID 35898868, 2022). "In recent studies, we identified the likely cause of Glo1-linked MDR in cancer chemotherapy." (PMID 35269594, 2022).
cancer (continued). "Generally, improving the understanding of glyoxalases in cancer pathogenesis will help assess the importance of the further source of biomarkers for tumor prognosis associated with the D-lactate metabolism, especially since GLO1 is linked to multidrug resistance in cancer chemotherapy." (PMID 36612084, 2022). "GLO1 has been investigated and linked to studies of tumor growth and cancer therapy." (PMID 34440621, 2021). "Indeed, higher levels of Glo1 have been described in several cancers and have also been linked to multidrug resistance (MDR) in cancer chemotherapy." (PMID 33869040, 2021). "Increased Glo1 expression is also associated with multidrug resistance in cancer chemotherapy." (PMID 33396745, 2020). "Glo-1 overexpression is associated with cancer cell survival and resistance." (PMID 28698611, 2017). "Glo1 overexpression was linked to MDR in cancer chemotherapy of other tumour types." (PMID 29100361, 2017). "Given their roles in AGE formation and cytotoxicity, GLO1 and MG have been implicated in diseases where these effects are relevant to pathogenesis, such as diabetic complications (i.e., micro- and macro-vascular disease), cancer, and aging." (PMID 23181072, 2012). "In the curent study, pan-cancer analysis revealed elevated GLO-1 mRNA levels across various malignancies, exhibiting variable prognostic implications on patient survival: reduced survival in ACC, MESO, and SARC, and enhanced survival in KIRC and LIHC." (PMID 40727469, 2025). "Analysis using the EPIC algorithm revealed substantial correlations between GLO-1 expression and immune infiltration in a larger set of 41 cancer types." (PMID 40727469, 2025). "Our findings suggest that GLO-1 contributes to cancer progression by fostering an immunosuppressive microenvironment through MG-H1-mediated upregulation of the immune checkpoint programmed death ligand 1 (PD-L1)." (PMID 40727469, 2025). "Our findings establish GLO-1 as a promising prognostic biomarker with potential clinical significance in multiple cancer types." (PMID 40727469, 2025). "In summary, our study highlights GLO-1 as a significant biomarker across multiple cancers that plays a key role in cancer progression, immune modulation, and therapeutic response." (PMID 40727469, 2025). "It shows how increased GLO-1 influences chemotherapy response, glycation end products, and apoptosis in cancer cells." (PMID 40727469, 2025). "An excessive glycolytic flux generates higher amounts of MGO (and D-lactate), therefore cancer cells produce more Glo1 to compromise MGO toxicity." (PMID 40141037, 2025). "In turn, chronic inflammation can also inhibit GLO1 activity, leading to further accumulation of MG, thus creating a vicious cycle that promotes cancer development, thus forming a closed loop." (PMID 40352588, 2025). "We first explored GLO1 mRNA expression levels in tumor and normal tissues using pan‐cancer datasets, and the results showed that GLO1 mRNA expression levels were significantly upregulated in most cancer types." (PMID 40492378, 2025). "While this study provides valuable insights into GLO-1’s role in cancer, it has certain limitations that should be acknowledged." (PMID 40727469, 2025). "First, the precise mechanisms by which ACh regulates Glo1 and MG-H1 in cancer cells need to be explored in more detail." (PMID 40362346, 2025). "In this study, we investigated GLO-1 expression in a diverse range of cancer types and analyzed its role in cancer immunopathology." (PMID 40727469, 2025). "Our pan-cancer analysis of GLO-1 revealed differential expression across various cancer stages, suggesting its potential as both a tumorigenic and prognostic marker." (PMID 40727469, 2025). "This study identifies a novel pathway in which the E3 ubiquitin ligase, praja ring finger ubiquitin ligase 1 (PJA1), mediates the proteasomal degradation of glyoxalase I (GLO1) exclusively in ferroptosis‐sensitive cancer cells." (PMID 40908564, 2025).
cancer (continued). "Inhibition of GLO-1 impairs MG detoxification, leading to intracellular dicarbonyl stress that compromises cancer cell survival." (PMID 40727469, 2025). "We posit that the tissue type, local Glo1 expression levels, and different metabolic and signaling pathways interact in a complex manner to regulate the levels of methylglyoxal in different cancer types." (PMID 40166206, 2025). "To further investigate the potential regulatory mechanisms influencing GLO-1 expression in cancer, we examined DNA methylation alterations as a key epigenetic modification." (PMID 40727469, 2025). "Our findings provide further evidence supporting the potential of GLO-1 as both a valuable prognostic marker and a promising therapeutic target in cancer." (PMID 40727469, 2025). "While GLO1 was initially considered an oncogene due to its increased expression and amplification in cancer, genetic studies have instead identified GLO1 as a tumor suppressor gene." (PMID 40002398, 2025). "Glo1 expression in cancer cells is elevated to prevent increased intracellular MGO concentrations, leading to LGSH production." (PMID 40128358, 2025). "We posit that the tissue type, local Glo1 expression levels, and different metabolic and signaling pathways interact in a complex manner to regulate the levels of MG in different cancer types." (PMID 40705923, 2025). "In recent years, targeting MG metabolism by developing MG scavengers and GLO1 modulators has emerged as a promising strategy for cancer therapy." (PMID 40352588, 2025). "In clinical investigations, GLO1 expression correlates negatively with cancer survival, and a predominant nuclear staining has been reported." (PMID 40650119, 2025). "A key distinction is that GLO-1 expression levels vary in cancer; often being upregulated, while GLO-2 expression generally remains consistent in both normal and malignant cells." (PMID 40727469, 2025). "Oxidation of GLO1 at Cys139 was previously recognized as a P-SSG that deactivates the enzyme and has been linked to DNA damage and apoptosis in cancer cells." (PMID 41389768, 2025). "MG accumulation in cancer cells, especially when GLO1 is inhibited, significantly promotes apoptosis in tumor cells." (PMID 40352588, 2025). "The expression and activity of GLO1 in certain cancer cells have been shown to correlate with tumor progression, indicating a significant role for GLO1 in carcinogenesis." (PMID 40002398, 2025). "In summary, targeted GLO1 inhibition therapy can effectively improve the sensitivity of tumor treatment by selectively utilizing the accumulation of MG toxicity in cancer cells, especially showing outstanding value in the treatment of drug-resistant tumors." (PMID 40352588, 2025). "The primary therapeutic application of GLO1 inhibitors is cancer chemotherapy, particularly for tumors exhibiting high GLO1 expression." (PMID 40492378, 2025). "Despite these findings, the clinical significance of GLO-1 expression and its role in cancer immunopathology remains relatively unexplored." (PMID 40727469, 2025). "To elucidate the potential role of GLO-1 in modulating the response to cancer immunotherapy, we analyzed the correlation between GLO-1 expression and key immunotherapeutic biomarkers: TMB, MSI, and a panel of ICP." (PMID 40727469, 2025). "Our findings suggest that GLO1 methylation as a potential biomarker for gene expression regulation in specific cancers." (PMID 40727469, 2025). "Further, Glo1 copy number amplification has been observed in ∼8% of all human cancers, indicating high endogenous MG levels in the tumor microenvironments." (PMID 40705923, 2025). "Amplification of the Glo1 gene is a common genetic event in various cancers, with higher expression observed in aggressive and invasive tumor cells." (PMID 38398772, 2024). "Analyses of scRNA-seq data and public gene expression datasets corroborated the overexpression of GLO1 and its involvement in cancer metabolism, particularly glycolysis." (PMID 38870176, 2024).